MMP9 (matrix metallopeptidase 9)
Diseases named in the same sentence as MMP9 in open-access papers (continued):
Sharing a sentence is not in itself a finding about the gene and the disease.
Myocardial fibrosis (continued). "For example, exercise can promote the release of exosomes containing high levels of miR-455, miR-29b, miR-323-5p, and miR-466 by cardiomyocytes, and the miRNAs in these exosomes can inhibit MMP-9 activity and block ECM remodeling, thereby reducing myocardial fibrosis in db/db mice." (PMID 40182630, 2025). "Taking into account the assessment of myocardial fibrosis markers, there were no significant changes in the concentration of matrix metallopeptidase 9 (MMP-9) and tissue inhibitors of metalloproteinases 1 (TIMP-1) in the study group." (PMID 38928407, 2024). "In addition, TNF-α directly reduces collagen synthesis in cardiomyocytes, enhances matrix metallopeptidase 2 (MMP-2) and matrix metallopeptidase 9 (MMP-9) activities, promotes collagen breakdown, and exacerbates myocardial fibrosis." (PMID 37057099, 2023). "Matrix metalloproteinase 9 (MMP-9) could degrade the ECM and plays an important role in the compensation of myocardial fibrosis." (PMID 35264961, 2022). "Interestingly, an opposite course with HCD was seen between the MMP2 and MMP9 collagen-degrading proteins and the profibrotic TIMP1, suggestive of increasing myocardial fibrosis." (PMID 34449561, 2021). "Moreover, transplantation of cell sheets consisting of myoblasts or NMCs showed a significant attenuation in myocardial fibrosis and expression of fibrosis-related genes, such as MMP2 and MMP9 as compared with the control group." (PMID 32070429, 2020). "The cardiac function parameters were evaluated by echocardiographic; the serum NT-BNP level was detected by ELISA; the degree of myocardial fibrosis was observed through masson staining; the expression of MMP-2, MMP-9 in the cardiac were got by immunohistochemistry." (PMID 29739333, 2018). "Consistent with the protective effect ofNAC on cardiac pathophysiological changes, real-time RT-PCR analysis of the mRNAexpressions that related to cardiac hypertrophy and myocardial fibrosis, such asα-MHC, β-MHC, ANP, BNP, Col1a1, Col3a1, Mmp2,and Mmp9, also showed the similar trend." (PMID 27443826, 2016). "Then the myocardial fibrosis increased and survival rate decreased in mice after neutralizing IL-22, accompanied by a decline in Th22 cell number, reduced IL-22, diminished IL-22R expression and increased indicators of myocardial fibrosis such as COL1-A1, COL3-A1, MMP9." (PMID 25547181, 2014). "In addition, our study demonstrated that the protein expression levels of MMP-9 and TIMP-1 were correlated with the levels of myocardial fibrosis in the LA with ageing and/or in AF." (PMID 23403858, 2013). "Notably, EA was effective in reversing the expression patterns of TNF-α and MMP-9 in SHR (P < 0.01, P < 0.001), which might mediate the inhibitory effects of EA on myocardial hypertension and myocardial fibrosis." (PMID 32982761, 2020). "Electroacupuncture at PC6 inhibited myocardial fibrosis on hypertension-induced myocardial fibrosis in spontaneously hypertensive rats (SHRs), which may be mediated by down-regulation of the enhanced Ang II-TGF-β1-CTGF/TNF-α pathway and up-regulation of the reduced MMP-9 expression." (PMID 35578250, 2022). "Collectively, the results of present study suggest that 8 weeks of EA at PC6 inhibited myocardial fibrosis in SHRs, which might be mediated by downregulation of an enhanced Ang II -TGF-β1-CTGF/TNF-α pathway as well as upregulation of the diminished expression of MMP-9." (PMID 32982761, 2020).
epilepsy (71 papers, 2011 to 2025). A brain disorder characterized by episodes of abnormally increased neuronal discharge resulting in transient episodes of sensory or motor neurological dysfunction, or psychic dysfunction. "Several clinical studies have observed a potential association between changes in serum MMP-9 levels and epilepsy." (PMID 38449733, 2024). "In individuals with epilepsy or neuroinflammatory diseases, increased blood and cerebrospinal fluid MMP-9 were associated with blood-brain barrier disruptions and leakage." (PMID 38431757, 2024). "In summary, we found that lncRNA ILF3AS1, miRNA-212, MMP3, and MMP9 have predictive and diagnostic powers for epilepsy, with AUC values of 0.656, 0.965, 0.659, and 0.738, respectively." (PMID 39268188, 2024). "We conducted a comprehensive search of Embase, Web of Science, PubMed, Cochrane Library, WanFang DATA, VIP, and the CNKI to identify studies that investigate the potential association between MMP-9 and epilepsy." (PMID 38449733, 2024). "This work is the first meta-analysis to investigate the association between serum MMP-9 level and epilepsy." (PMID 38449733, 2024). "MMP9 also contributes to parvalbumin positive inhibitory interneuron (PVIN) cell loss that is found in epilepsy." (PMID 36035987, 2022). "According to recent studies, MMP-9 is thought to be strongly associated with the pathogenesis of many neurological disorders, such as Alzheimer’s disease, stroke, seizures and epilepsy." (PMID 33377994, 2021). "In this regard, high levels of MMP-9 have been found in patients suffering of various types of epilepsy and Fragile X syndrome, in which many patients show high susceptibility to epilepsy." (PMID 30044455, 2018). "Brain injury in acute PM involves an upregulation of MMP activity, measurable in the CSF of infected patients with higher MMP-9 level being associated with the development of hearing impairment or secondary epilepsy in infected children." (PMID 30131074, 2018). "In next paragraphs the effects of MMP-9 activity and its associations with epilepsy will be presented." (PMID 28104930, 2016). "Attention has also been paid to an association of MMP-9 with inflammatory processes and blood-brain barrier damage in the context of epilepsy." (PMID 28104930, 2016). "Enhanced levels of Matrix Metalloproteinase-9 (MMP-9) have been implicated in the pathogenesis of epilepsy in humans and rodents." (PMID 27505431, 2016). "In this review we will try to recapitulate the results of previous studies about MMP-9 in terms of its association with epilepsy." (PMID 28104930, 2016). "Doxycycline hyclate, an antibiotic that inhibits MMP-9, prevents the loss of PNNs after kindling and delays epilepsy onset, possibly through the inhibition of MMP-9." (PMID 26283917, 2015). "Therefore, a standardized study with a larger sample size must be conducted to verify the outcomes and establish the precise association between the MMP-9 level and the etiology, diagnosis, prognosis, and seizure status of epilepsy." (PMID 38449733, 2024). "The downregulation of mBDNF was observed in MMP9-deficient mice after kindling-induced epilepsy." (PMID 34440823, 2021). "Interestingly, in kindling-induced epilepsy, MMP9 activity is associated with the pruning of dendritic spines and aberrant synaptogenesis after mossy fiber sprouting in hippocampus." (PMID 31868167, 2019). "Future studies should investigate whether early interventions to lower post-injury MMP-9 levels can prevent pathophysiological processes and reduce the risk of developing epilepsy." (PMID 29667129, 2018). "Recent studies suggested that ictogenesis might be associated with high levels of MMP-9 in patients suffering of various types of epilepsy." (PMID 30044455, 2018). "The association between MMP-9 with drug-resistance of epilepsy has also been noticed." (PMID 28104930, 2016).
epilepsy (continued). "Seizure-induced MMP-9 expression was previously shown to be localized to dendrites and synapses and implicated in synaptic remodeling and mossy fiber sprouting, pathological structural phenomena associated with epilepsy." (PMID 25071472, 2014). "Therefore, the concentration of MMP-9 in serum may be used as a peripheral marker of neuronal injury and neuroinflammation in the brain associated with epilepsy." (PMID 38449733, 2024). "Thus, SAH may induce epilepsy through the regulation of pathogenic pathways by immune-related genes (IRGs), such as the expression levels of the MMP9 and C3AR1 genes in the immunoregulatory pathways leading to the occurrence of epilepsy." (PMID 36741285, 2023). "Finally, we review research that implicates MMP-9 in aberrant synaptic plasticity and spine dysmorphology in neurological disorders, with a focus on morphological abnormalities of dendritic protrusions that are associated with epilepsy." (PMID 25071472, 2014). "In the epilepsy model, high-frequency discharges activate the Ca2+/calpain-matrix metalloproteinase-9 (MMP-9) cascade, inducing an increase in the expression of ADAMTS4." (PMID 41155465, 2025). "MMP-9 and S100B, the proteins involved in blood-brain barrier integrity, are widely studied as biomarkers in many diseases, including epilepsy." (PMID 40076533, 2025). "Increased expression of MMP-9 has previously been found in epileptogenic brain tissue of patients after status epilepticus, in patients with drug-resistant epilepsy and in a post-SE rat model of epileptogenesis linking MMP-9 to epileptogenesis." (PMID 41356251, 2025). "When comparing our results to previous studies on epilepsy, the increases in MMP-9 and S100B levels after seizures appear to be higher and more prolonged." (PMID 40076533, 2025). "Previous studies have demonstrated that tonic–clonic seizures in individuals with epilepsy result in elevated serum concentrations of MMP-9 and S100B." (PMID 40076533, 2025). "MMP-9 and S100B, the proteins involved in blood-brain barrier integrity, are particularly interesting because they are increased in epilepsy patients in the interictal period and are triggered by the seizures themselves." (PMID 40076533, 2025). "In epilepsy, MMP-9 levels are higher compared to the age- and sex-matched control group and increase after tonic–clonic seizures reaching the level by about 2 times higher than the age-matched control." (PMID 40076533, 2025). "Tracking MMP-9 levels in serum has the potential to contribute to early detection, prognosis, and evaluation of therapeutic responses across various forms of epilepsy, establishing it as a promising biomarker in clinical diagnostics." (PMID 38255970, 2024). "This meta-analysis presents the first comprehensive summary of the connection between serum MMP-9 level and epilepsy." (PMID 38449733, 2024). "The increased MMP-9 can also rearrange the molecular structure of peripheral cells and cellular matrix, resulting in synaptic remodeling, which can lead to epilepsy." (PMID 38449733, 2024). "We aimed to assess the serum expressions of the lncRNAs ILF3AS1, MMP3, and MMP9 along with microRNA-212 (miRNA-212) as predictive biomarkers in children with epilepsy; we also assessed their correlations with magnetic resonance imaging (MRI) findings." (PMID 39268188, 2024). "The subgroup analysis of country showed that serum MMP-9 levels were higher in Chinese, Polish and Egyptian patients with epilepsy than in controls, with more pronounced in Egypt." (PMID 38449733, 2024). "The subgroup analysis of the seizure types demonstrated substantial difference in the MMP-9 levels between patients of seizure-free epilepsy (patients who have been seizure-free for at least 7 days) and the control group." (PMID 38449733, 2024). "This study presents evidentiary support that levels of MMP-9 are significantly elevated in individuals with epilepsy." (PMID 38449733, 2024).
epilepsy (continued). "Two studies reported serum MMP-9 levels in male and female epilepsy patients and matched controls at 1–3, 24, and 72 h after seizure." (PMID 38449733, 2024). "We reviewed current studies on the relationship between serum MMP-9 level and epilepsy and evaluated the potential of MMP-9 as a marker of epilepsy." (PMID 38449733, 2024). "The results showed significantly higher levels of lncRNAs ILF3AS1, MMP3, and MMP9 as well as lower levels of miRNA-212 in children with epilepsy compared to the controls." (PMID 39268188, 2024). "Within the framework of epilepsy, MMP-9 assumes a diverse role, impacting different facets of the condition." (PMID 38255970, 2024). "Previous studies revealed a correlation between higher MMP-9 levels and neurocognition in attention-deficit/hyperactivity disorder, epilepsy, or systemic lupus erythematous." (PMID 38431757, 2024). "We gained a clearer understanding of how MMP-9 in serum functions as a biological marker of epilepsy through the subgroup analysis of country, age category, seizure types, and duration of seizures." (PMID 38449733, 2024). "The subgroup analysis of seizure types also indicated high serum MMP-9 levels in patients of seizure-free epilepsy (patients who have been seizure-free for at least 7 days) and those with epileptic seizures compared with the healthy control group." (PMID 38449733, 2024). "The meta-analysis that included serum MMP-9 data for all epilepsy patients supported a significant increase in MMP-9 in epilepsy patients compared with the control group (SMD = 4.18, 95% CI = 2.18–6.17, p < 0.00001)." (PMID 38449733, 2024). "The serum lncRNA ILF3AS1 expression levels were higher in children with epilepsy and were associated with higher levels of MMP3 and MMP9 as well as lower levels of miRNA-212 than those in the control group." (PMID 39268188, 2024). "This meta-analysis aims to provide useful evidence for the continuous and in-depth study of serum MMP-9 in epilepsy in the future." (PMID 38449733, 2024). "The subgroup analysis of the age category demonstrated that the serum MMP-9 levels of the adult patients with epilepsy were significantly higher than those of the matched controls." (PMID 38449733, 2024). "The meta-analysis indicated that the serum MMP-9 level was higher in epilepsy patients (SMD = 4.18, 95% confidence interval = 2.18–6.17, p < 0.00001) compared with that in the control group." (PMID 38449733, 2024). "Four studies reported serum MMP-9 levels in epilepsy patients and matched controls at 1–3, 24, and 72 h after seizure." (PMID 38449733, 2024). "The detection of MMP-9 is crucial in the early diagnosis of epilepsy, the evaluation of treatment effectiveness, prognosis, and determination of the key medical interventions." (PMID 38449733, 2024). "After the combined analysis, substantial difference in MMP-9 levels can be observed between patients with seizure-free epilepsy (SMD = 2.65, 95% CI = 0.66–4.65, p = 0.009)." (PMID 38449733, 2024). "Three of the eight studies that analyzed serum samples mentioned the serum MMP-9 level in patients with epilepsy (patients who have been seizure-free for at least 7 days)." (PMID 38449733, 2024). "The subgroup analysis of country indicated that the epilepsy patients in China, Poland, and Egypt had higher levels of serum MMP-9 than the control group, with the increase being more pronounced in Egypt." (PMID 38449733, 2024). "Large-scale studies with a high level of evidence are necessary to determine the exact relationship between MMP-9 and epilepsy." (PMID 38449733, 2024). "The bioinformatics analysis results from the GSE36791 and GSE143272 datasets indicated that two genes—MMP9 and C3AR1—were strongly associated with SAH complicated with epilepsy." (PMID 36741285, 2023). "The MMP9 gene exerts profound effects on epilepsy by regulating immune cell infiltration and inflammation." (PMID 36741285, 2023).
epilepsy (continued). "Serum MMP-9 was also showed to be increased in a general population of patients with epilepsy, but the precise time from the last seizure was either not mentioned or fitted in a broad range, starting from 0 days." (PMID 36766708, 2023). "The most studied MMP in epilepsy is MMP-9, and it would be interesting to measure its levels in our model after VNS." (PMID 38203262, 2023). "In a study comparing unruptured bAVMs to control tissue from epilepsy patients, unruptured bAVMs had increased levels of MMP-9 protein and increased activity of MMP-9 and MMP-2 (measured via gelatin zymography)." (PMID 38001877, 2023). "In the present study, higher MMP-9 and C3AR1 levels in SAH were associated with the incidence of epilepsy after SAH." (PMID 36741285, 2023). "Expression of MMP-2 and MMP-9 increases in the brain of patients with epilepsy, and serum levels of MMP-9 are elevated after seizures." (PMID 36499038, 2022). "MMP9 is upregulated in epilepsy models, and this ECM proteinase has been shown to degrade the specialized ECM called perineuronal nets (PN) surrounding PVINs." (PMID 36035987, 2022). "It is well-established that matrix metallopeptidase 9 (MMP-9) is a critical protein inducing the development of epilepsy in humans and rodents, and excess MMP-9 enhances the incidence of seizures." (PMID 36311022, 2022). "Several MMPs were upregulated in animal models of epilepsy, including MMP9, MMP2, 14, MMP3, and MMP13." (PMID 34440823, 2021). "Li and colleagues studied MMP9 expression in TSC and focal cortical dysplasia (FCD), another malformation of cortical development and a well‐known cause of pharmacoresistant epilepsy." (PMID 31183875, 2020). "MMP-9 is indeed the predominant gelatinase involved in epilepsy and has been proposed to be a potential therapeutic target." (PMID 32372941, 2020). "Excitotoxicity leading to neuronal and hippocampal apoptosis in conjunction with high MMP-9 activity was observed in kainate-induced epilepsy models." (PMID 31312171, 2019). "The best examined proteinase with a significant role in different models and types of epilepsy appears to be MMP-9." (PMID 31172215, 2019). "Some authors have focused on the importance of MMP-9 as damage and remodeling biomarkers in cancer, multiple sclerosis, epilepsy, and heart disease." (PMID 31578449, 2019). "In animal models, the MMP-9 inhibitor, S24994, has a protective role on the hippocampus in kainate-induced epilepsy." (PMID 31312171, 2019). "MMP-9-related synaptic plasticity has been shown to play an important role in the development of epilepsy in both humans and rodents." (PMID 29667129, 2018). "Since MMP-9 is also associated with neuronal death, aberrant synaptic plasticity and inflammation, all of them occurring during epileptogenesis, MMP-9 has become a potential therapeutic target in epilepsy." (PMID 30044455, 2018). "For instance, the upregulation of MMP9 has been found to induce excessive excitatory synaptogenesis in rodent epilepsy models." (PMID 28794441, 2017). "A decrease of MMP-9 level in the saliva of all patients with epilepsy was reported and it was most significant in the patients with the unsatisfactory control of the disease." (PMID 28104930, 2016). "The study, apart from noting the association of the decrease in MMP-9 level in saliva with the occurrence and activity of epilepsy, also shows a possibility of noninvasive evaluation of MMP-9 level." (PMID 28104930, 2016). "The synaptic plasticity–related protease Matrix Metalloproteinase-9 (MMP-9) is an important stimulant for the development of epilepsy in humans and rodents." (PMID 27505431, 2016). "Subsequently, we detected strong epileptogenesis-induced dissociation of the repressive transcription factor YY1 from the Mmp-9 proximal promoter chromatin occurring at early stages of epilepsy development by ChIP." (PMID 27505431, 2016).